CYP17A1 (cytochrome P450 family 17 subfamily A member 1)
Diseases named in the same sentence as CYP17A1 in open-access papers (continued):
Sharing a sentence is not in itself a finding about the gene and the disease.
vitamin D deficiency (2 papers, 2024). A nutritional condition produced by a deficiency of VITAMIN D in the diet, insufficient production of vitamin D in the skin, inadequate absorption of vitamin D from the diet, or abnormal conversion of vitamin D to its bioactive metabolites. "Enzymes like StAR, 17β-HSD, 3β-HSD, CYP11A1, and CYP17A1 are crucial for androgen synthesis in Leydig cells, with calcitriol shown to up-regulate CYP11A1 and CYP17A1 and increase 3β-HSD levels; conversely, vitamin D deficiency can decrease StAR, 3β-HSD, CYP11A1, and CYP17A1 expression in the testes." (PMID 38698459, 2024).
acne (1 paper, 2021). An inflammatory process of the sebaceous glands which is characterized by comedones, nodules, papules and/or pustules on the skin. "Nevertheless, we found that TNF rs1800629 A allele carriers and CYP17A1 rs743572 T allele carriers had significantly reduced mild acne risk [pOR: 0.60; 95% Confidence Interval (CI): 0.33–0.86] and severe acne risk (pOR: 0.59; 95% CI: 0.40–0.79), respectively, across populations." (PMID 33849530, 2021). "This systematic review and meta-analysis suggest that genes influencing inflammatory responses, specifically TNF, and genes influencing the function and activity of sebaceous glands, specifically CYP17A1 and FST, have potential risk variants for acne presentation and severity across populations." (PMID 33849530, 2021). "Another CYP17A1 SNP rs743572 was investigated in three studies—two studies reported significant association with acne and acne severity, while another did not." (PMID 33849530, 2021). "Begg’s funnel plot and Egger’s test showed that there was statistically significant publication bias for the meta-analysis of TNF rs1800629 acne presentation, mild acne and severe acne; SELL rs7531806; PPARG rs1801282; and CYP17A1 rs743572 acne presentation, moderate acne and severe acne." (PMID 33849530, 2021).
androgen insensitivity syndrome (1 paper, 2021). Androgen insensitivity syndrome (AIS) is a disorder of sex development (DSD) characterized by the presence of female external genitalia, ambiguous genitalia or variable defects in virilization in a 46,XY individual with absent or partial responsiveness to age-appropriate levels of androgens. "The median PSAI score was similar to the control males in 5α-RD2, PAIS, and NR5A1 gene mutation groups (p > 0.05); while identical to the control females in complete androgen insensitivity syndrome (CAIS) and CYP17A1 gene mutation groups (p > 0.05)." (PMID 34627348, 2021).
Arthralgia (1 paper, 2021). "SNPs in steroid 17-alpha-hydroxylase/17,20 lyase (CYP17A1) and vitamin D3 receptor (VDR) genes were significantly associated with treatment-related arthralgia (p = 0.003 and p = 0.012, respectively)." (PMID 33530456, 2021).
brain tumor (1 paper, 2017). "In the oncomine database, CYP17A1 messenger RNA (mRNA) was significantly increased in brain tumor tissues compared with normal brain tissues." (PMID 28530704, 2017).
cardiac hypertrophy (1 paper, 2015). "Thus, CYP17A1 may contribute to cardiac hypertrophy in this clinical condition." (PMID 26263970, 2015). "The result supports a role of CYP17A1 in the modulation of LVMI and thus cardiac hypertrophy in this clinical condition." (PMID 26263970, 2015).
cholestasis (1 paper, 2014). Impairment of the bile flow caused by obstruction within the liver, or outside the liver in the bile duct system. "Recently, increased production of 17-hydroxy steroid metabolites, the product of Cyp17a1, have been associated with juvenile onset cholestasis." (PMID 25506828, 2014).
coronary atherosclerosis (1 paper, 2023). Atherosclerosis of the coronary vasculature. "When CYP17A1 is mutated or functional impaired, it may be involved in the occurrence and development of coronary atherosclerosis through a variety of ways." (PMID 37370070, 2023).
cyst (1 paper, 2025). A sac-like closed membranous structure that may be empty or contain fluid or amorphous material. "Bins with a CYP19A1+ activated granulosa identity (cluster g9) were detected in the large activated cyst-like follicles in the medulla, surrounded by CYP17A1+ theca cluster t2." (PMID 40858568, 2025).
depression (1 paper, 2025). "Following the analysis of the metabolic pathways, seven genes including ALOX5, LTA4H, CYP4Y, PLA2G2C, AKR1C1, AKR1D1 and CYP17A1 were employed to elucidate further the potential mechanisms underlying CS treatment of depression." (PMID 40370520, 2025).
Dysmenorrhea (1 paper, 2025). Pain during menstruation that interferes with daily activities. "As endometrial CYP17A1 levels are increased in patients with severe dysmenorrhea, we could hypothesise that DHEA and TRPM3 might play a key role in the pain perception during painful menstruation." (PMID 41154581, 2025).
endothelial dysfunction (1 paper, 2023). In vascular diseases, endothelial dysfunction is a systemic pathological state of the endothelium (the inner lining of blood vessels) and can be broadly defined as an imbalance between vasodilating and vasoconstricting substances produced by (or acting on) the endothelium. "It is conceivable that when CYP17A1 is mutated or functional impaired, it may cause long-term fluctuation of blood glucose and increase the level of free lipids, which can aggravate lipid toxicity and glucose toxicity, further increase oxidative stress, cause endothelial dysfunction." (PMID 37370070, 2023).
epilepsy (1 paper, 2021). A brain disorder characterized by episodes of abnormally increased neuronal discharge resulting in transient episodes of sensory or motor neurological dysfunction, or psychic dysfunction. "Other common genes including MTHFR, GSTM1, CYP17A1, and CACNB2 are implicated in neurological disorders such as epilepsy." (PMID 34899152, 2021). "Bioinformatics analysis revealed that the effects of AS3MT on epilepsy likely involved multiple targets including MTHFR, GSTM1, CYP17A1, NT5C2, YBX3, CNNM2, CACNB2, and TRIM26." (PMID 34899152, 2021). "The effects of AS3MT on epilepsy might involve multiple targets including CNNM2, CACNB2, TRIM26, MTHFR, GSTM1, CYP17A1, NT5C2, and YBX3." (PMID 34899152, 2021).
glucocorticoid deficiency (1 paper, 2019). "Glucocorticoid deficiency is rarely life-threatening in CYP17A1 deficiency, as increased corticosterone exerts some glucocorticoid receptor activation." (PMID 31294783, 2019). "Although milder forms of CYP17A1 deficiency have been reported, where only sex steroid production seems to be present (so-called “isolated 17,20-lyase deficiency”), stimulated cortisol levels do not rise sufficiently in these patients, indicating glucocorticoid deficiency." (PMID 31294783, 2019).
glucose metabolism disorders (1 paper, 2023). "In agreement with our results, we find that CYP17A1 mutations are associated with a significant reduction in the amount and efficiency of glucose transporters, leading to glucose metabolism disorders." (PMID 37370070, 2023).
gonadal dysgenesis (1 paper, 2024). A congenital disorder characterized by the presence of extremely hypoplastic gonads preventing the development of secondary sex characteristics. "We detected all the variants in heterozygosis, except one in the CYP17A1 gene in two siblings with PCC and gonadal dysgenesis." (PMID 39596125, 2024).
hyperuricemia (1 paper, 2023). An abnormally high level of uric acid. "Other enzymes, such as cytochrome P450 family 17 subfamily A member 1 (CYP17A1) and 21-hydroxylase (CYP21A1), showed no significant changes under hyperuricemia conditions." (PMID 38034015, 2023).
hypocortisolism (1 paper, 2016). "Studies in goats have indicated that the expression of CYP17A1 (cytochrome P450 17A1) causes hypocortisolism in Angora goats in South Africa." (PMID 26814503, 2016).
intrahepatic cholestasis (1 paper, 2025). A cholestasis characterized by impairment of the bile flow caused by obstruction located in the liver. "Pathogenic prediction for five missense variants of the ESR2, CYP1A2, and CYP17A1 genes in 249 Han Chinese people with intrahepatic cholestasis of pregnancy." (PMID 40933484, 2025).
liver cancer (1 paper, 2021). An epithelial or non-epithelial malignant neoplasm that arises from the liver. "Furthermore, CYP2W1 can be used as an independent prognostic biomarker in liver cancer, and CYP17A1 can be used as a molecular marker in the diagnosis of liver cancer." (PMID 35003516, 2021).
mental disorder (1 paper, 2020). A disease that has its basis in the disruption of mental process. "A potentially overarching functional implication of this locus in both somatic and mental disorders is supported by the fact that in adolescent males but not females, a CYP17A1 SNP was associated with enhanced blood pressure reactivity to mental stress." (PMID 32373164, 2020).
methemoglobinemia (1 paper, 2025). An inherited or acquired condition characterized by abnormally increased levels of methemoglobin in the blood. "Cytochrome b5 (b5) is familiar to endocrinologists for promoting the 17,20-lyase activity of P450c17 (CYP17A1), thus regulating the synthesis of androgen precursors; but the principal action of b5 is the reduction of methemoglobin, and b5 deficiency causes DSD with methemoglobinemia." (PMID 39574227, 2025).
orchitis (1 paper, 2021). Inflammation of one or both testes due to viral or bacterial infections. "More interestingly, Cd59a, which also correlated positively with Star, Cyp17a1, and androgen synthesis in Lc_Nt, was shifted to a weak negative correlation with androgen synthesis during orchitis." (PMID 35111154, 2021).
ovarian diseases (1 paper, 2024). "Conversely, several downregulated genes crucial for folliculogenesis were also found to be linked to ovarian diseases, namely, genes for sex hormone biosynthesis such as STAR, CYP17A1, and ALDH1A1, along with genes required for follicle development, such as INHA." (PMID 38126810, 2024).
paraganglioma (1 paper, 2024). A benign or malignant neoplasm arising from paraganglia located along the sympathetic or parasympathetic nerves. "It was found that in PCPG (pheochromocytoma/paraganglioma), there was a co-expression between SULT1E1 and CYP17A1 (SULT1E1-CYP17A1), SULT1E1-CYP21A2, SULT2A1-CYP17A1, and SULT2A1-CYP21A2 genes, with Pearson correlation coefficients (R) equal to 0.60, 0.56, 0.81, and 0.73, respectively." (PMID 38396748, 2024).
Sepsis (1 paper, 2022). Sepsis is defined as life-threatening organ dysfunction caused by a dysregulated host response to infection. "Moreover, VD can significantly increase the mRNA expression of STAR, CYP17A1, and CYP21 proteases in adrenal cortex cells, and intragastric administration of VD to sepsis model rats can increase the serum cortisol level in vivo." (PMID 36338128, 2022).
tumor (66 papers, 2009 to 2026). "Finally, abiraterone-treated tumor xenografts revealed 2-fold upregulation of CYP17A1, and cell-free CYP17A1 copy number variations were associated with poorer outcomes in abiraterone-treated patients." (PMID 28604629, 2017). "Abiraterone acetate is a prodrug of abiraterone, which irreversibly inhibits CYP17A1, an enzyme critical to androgen biosynthesis in the testes, adrenal glands, and within the tumor microenvironment." (PMID 40542935, 2025). "By blocking both the 17α-hydroxylase and 17,20-lyase activities of CYP17A1, abiraterone markedly reduces the synthesis of testosterone and other androgens, including those produced inside the tumor, which are central drivers of CRPC progression." (PMID 41235005, 2025). "Abiraterone acts as a selective and irreversible inhibitor of CYP17A1, a critical enzyme in the steroidogenesis pathway responsible for androgen production in the testes, adrenal glands, and tumor microenvironment." (PMID 40918764, 2025). "On the other hand, intratumoral secretion of enzymes involved in testosterone synthesis, such as CYP17A1, supports tumor survival and growth." (PMID 39598525, 2024). "Conversely, a positive association was found between tumor purity and the expression levels of YTHDC1, EIF3A and CYP17A1 (average PCC = 0.42)." (PMID 38171932, 2023). "Among the five RMScore genes, four (ANLN, KRT6A, PITX3, and NTSR1) were identified to be upregulated, while CYP17A1 was identified to be downregulated in TCGA-LUAD tumor tissues compared with paired normal tissues." (PMID 35859664, 2022). "Subsequently, we found that overexpression of SAR1 significantly prevented abiraterone-induced cell death, suggesting that the tumor-suppressive effect of CYP17A1 inhibition is mediated by the downregulation of SAR1a/b." (PMID 31527549, 2019). "Altogether, the results indicate that MDA-PCa-133 tumor growth in castrate mice was due to increased expression of AR and its ligand-independent isoform AR-V7, as well as CYP17A1, which is required for intratumoral testosterone biosynthesis." (PMID 27748439, 2016). "Specifically in patients treated with Abiraterone, maintenance of androgens in the tumour cells can be sustained by overexpression of CYP17A1." (PMID 27583544, 2016). "In any event, we conclude that salinomycin can potentially lower tumor cell androgen levels by inhibiting CYP17A1 and HSD3β1, thereby further restricting AR signaling." (PMID 27557496, 2016). "This pattern appears to be a recurrent theme in molecular drug responses: for example, very recently it was reported that CYP17A1 level was markedly increased in tumor biopsies from CRPC patients after CYP17A1 inhibitor therapy." (PMID 22849360, 2012). "Some of the most intense staining was observed for an antibody against CYP17A1, which localized to tumor cell cytoplasm." (PMID 19146682, 2009). "Abiraterone is an example of an irreversible inhibitor of CYP17A1 and can reduce tumor burden, prolong life and relieve symptoms as it inhibits both the 17α-hydroxylase and 17,20-lyase activities of CYP17A1 and therefore inhibits multiple steps in androgen biosynthesis." (PMID 40253525, 2025). "Similarly, in hormone-sensitive breast cancer, where estrogen signaling fuels tumor development, CYP17A1 has garnered attention." (PMID 40561159, 2025). "Therefore, many clinical trials and FDA-approved medications target the tumor via AR pathways, such as abiraterone acetate, a type of CYP17A1 inhibitor that blocks the synthesis of androgens, thus affecting tumor growth." (PMID 38398019, 2024). "Distinguished from CYP17A1-dependent steroids, Prog offers a dual advantage: a metabolic pathway independent of CYP17A1 expression and a plethora of neuroprotective effects that extend beyond tumor suppression." (PMID 39103871, 2024). "However, further work is required to elucidate the functional role of CYP17A1-catalyzed hydroxylation in tumor development." (PMID 31527549, 2019).
tumor (continued). "Furthermore, in the IHC analysis, the A/CPA tumor tissues showed a higher proportion of CYP17A1 immune-reactive cells and large clear cells." (PMID 29770148, 2018). "Oral VT-464 or AA also stimulated increased expression of full-length AR and AR-V7, suggesting that both CYP17A1 inhibitors may activate similar tumor adaptation mechanisms." (PMID 27748439, 2016). "Furthermore, therapy resistance developed under AA treatments has been explained by treatment-induced selection of tumour cells with elevated intratumoural expression of CYP17A1." (PMID 25332874, 2014). "Abiraterone acetate, an oral agent, acts as a selective and irreversible inhibitor of the CYP17A1 enzyme, which plays a critical role in the enzymatic conversion of steroid precursors such as pregnenolone and progesterone within the testes, adrenal glands, and tumor microenvironment." (PMID 41235005, 2025). "Six patients underwent molecular testing on tumor DNA: two carried marked IC2-LoM, two exhibited loss of heterozygosity (LOH) at chromosome 11p15, one carried somatic pathogenic variants of CTNNB1 and GNAS genes, and one carried somatic pathogenic variants of the MKRN3 and CYP17A1 genes." (PMID 39682154, 2024). "Interestingly, tumor size also weakly correlated positively with CYP17A1 expression in APA (rs = 0.297, p = 0.03) and there was a trend of a correlation between tumor size and the percentage of cells with a ZF-like cell morphology in APA (rs = 0.242, p = 0.08)." (PMID 31636604, 2019). "The downregulation of lipid metabolism-related genes like CYP17A1 and SQLE suggests the core reconfigures its metabolic pathways to support aggressive tumor behavior, focusing more on structural adaptation and motility." (PMID 40431665, 2025). "In this research, the ERGS was composed of 8 ERGs (CXCL9, CYP17A1, DRGX, ENTHD1, HAS1, LAIR2, RETN, and SPHKAP), some of which were pivotal to the tumor progression." (PMID 38600248, 2024). "Compared with normal tissues, three genes (CYP17A1, HACD1, and MTMR10) were down-regulated in tumor tissues, while the others were up-regulated." (PMID 35295857, 2022). "The difference in the expression of the five ADME genes (SLC16A1, SLC7A5, SLCO1B1, CYP17A1, and ABCC8) between tumor and normal tissues was significant and was closely correlated with the survival of patients with NSCLC." (PMID 34522968, 2021). "There was also a weak positive correlation between the ZF enzyme CYP17A1 expression in APA and tumor size, and a trend for a positive correlation between the percentage of ZF-like cells in APA and tumor size." (PMID 31636604, 2019). "IHC staining and western blot analyses revealed that both the A/CPA and pure APA tumor tissues were positive for CYP11B1, CYP11B2, and CYP17A1, implying that these tumors can produce both aldosterone and cortisol." (PMID 29770148, 2018). "Histopathological analysis identified tumor regions with non-uniformly high expression of CYP17A1 and CYP21A2." (PMID 41594178, 2026). "By blocking CYP17A1, abiraterone reduces testosterone production to extremely low levels, enhancing the suppression already achieved by ADT and targeting residual androgen sources that can drive tumor growth." (PMID 40542935, 2025). "Lathyrol and cisplatin inhibit the proliferation of RCC xenografts, reduce the protein expression levels of AR, CYP17A1, SPHK2, PARP1, E-cadherin, and ZO-1 in tumor tissues (P < 0.05), and promote the protein expression levels of N-cadherin, β-catenin, vimentin and α-SMA (P < 0.05)." (PMID 38965120, 2024). "AbA is a selective inhibitor of androgen biosynthesis through the potential and irreversible blockade of cytochrome P450 family 17 subfamily A member 1 (CYP17A1), resulting in the absence of androgens in the blood and within tumour cells." (PMID 39337362, 2024).